JUN (Jun proto-oncogene, AP-1 transcription factor subunit)
Diseases named in the same sentence as JUN in open-access papers (continued):
Sharing a sentence is not in itself a finding about the gene and the disease.
glioma (69 papers, 2008 to 2025). A benign or malignant brain and spinal cord tumor that arises from glial cells (astrocytes, oligodendrocytes, ependymal cells). "According to the CCK-8 assay, JUN overexpression alleviated both the 24 and 48 h suppression of glioma cell proliferation caused by T4O." (PMID 37375197, 2023). "T4O treatment causes JUN downregulation, thus leading to the inhibition of glioma cell proliferation and induction of ferroptosis." (PMID 37375197, 2023). "Finally, it is also noteworthy that pasireotide-treatment decreased the phosphorylation levels of key factors involved in the TGF-β signalling-pathway (associated with aggressiveness in gliomas), such as JUN (responsible for tumour-invasion)." (PMID 40268793, 2025). "JUN might be associated with glioma survival prognoses, and patients who express high levels of gliomas have shorter OS and DFS." (PMID 37375197, 2023). "Western blot analysis confirmed that DET downregulated EGFR and JUN in glioma cells, while molecular docking further verified the binding of DET to these targets." (PMID 39850823, 2024). "Subsequent construction of a protein-protein interaction (PPI) network, along with GO and KEGG enrichment analyses, highlighted EGFR and JUN as key prognostic targets for predicting five-year survival in glioma patients." (PMID 39850823, 2024). "DET also affects glioma cell death by inhibiting the expression of EGFR/JUN (DET's core targets) and the core components of PI3K/AKT pathway." (PMID 39850823, 2024). "JUN overexpression markedly suppressed the effects of T4O on glioma cell proliferation and ferroptosis." (PMID 37375197, 2023). "The JUN expression level in glioma tissues was found to be significantly higher compared to that in normal tissues in the TCGA and GTEx database data." (PMID 37375197, 2023). "It is interesting to note that, after treatment with T4O, the JUN levels were downregulated in the glioma cells." (PMID 37375197, 2023). "Based on a Western blot analysis, enhanced transfection with a JUN plasmid increases GPX4 protein expression in glioma cells." (PMID 37375197, 2023). "RT-qPCR and Western blotting revealed that both the JUN mRNA and protein levels were elevated in the glioma cells treated with T4O." (PMID 37375197, 2023). "In the present study, we found that T4O can suppress glioma cell proliferation and induced ferroptosis; the JUN mRNA levels were reduced in the glioma cells following the T4O treatment." (PMID 37375197, 2023). "Transcription factor PAX5 (Paired Box Gene 5) promotes gliomagenesis and cooperates with factors such as MYC, FOS, or JUN, which are highly expressed in gliomas." (PMID 36850002, 2023). "The T4O treatment reduced JUN’s activity and induced ferroptosis in the cells, inhibiting the proliferation of the glioma cells." (PMID 37375197, 2023). "The overexpression of JUN alleviated the suppressive effect of T4O on colony formation in the glioma cells, according to the colony formation assays." (PMID 37375197, 2023). "The overexpression of JUN in the glioma cells significantly increased the luciferase activity of the wild-type sequences in the GPX4 promoter region." (PMID 37375197, 2023). "In glioma samples, miR‐5188 expression was found to be an unfavourable factor and was positively associated with the mRNA levels of SP1 and c‐JUN, whereas negatively associated with the mRNA levels of FOXO1." (PMID 32902145, 2020). "Consistently, our study further confirmed the enhanced transcription of miR‐5188 regulated by c‐JUN in glioma progression." (PMID 32902145, 2020). "In glioma cells treated with temozolomide and nimustine, apoptosis was achieved through c-JUN mediated activation of BIM (BCL-2 interacting mediator of cell death)." (PMID 30042885, 2018). "The mechanism by which JUN promotes ferroptosis in gliomas was identified." (PMID 37375197, 2023). "Finally, several plasmids containing JUN were transfected into the glioma cells before the T4O treatment." (PMID 37375197, 2023).
glioma (continued). "T4O suppressed JUN transcription and significantly reduced its expression in the glioma cells." (PMID 37375197, 2023). "Several plasmids containing JUN were transfected into the glioma cells before the T4O treatment." (PMID 37375197, 2023). "Furthermore, the TCGA dataset showed that JUN expression increased with glioma grade and was highest in GIV gliomas." (PMID 36850002, 2023). "We searched for transcription factors that are positively co-expressed with EIF4EBP1 in gliomas and found EIF4EBP1 mRNA expression to be significantly and positively associated with the mRNA expression levels of MYBL2, FOXM1, ETS1, HIF-1A, JUN, E2F1, and E2F6 in the REMBRANDT dataset." (PMID 35228525, 2022). "The endogenous Co‐IP assay showed the interaction between SP1 and c‐JUN in glioma cells." (PMID 32902145, 2020). "Immunofluorescence showed the nuclear colocalization of SP1 and c‐JUN proteins in glioma cells." (PMID 32902145, 2020). "Collectively, the obtained data demonstrate that c‐JUN directly enhances miR‐5188 transcription, and there may exist a positive feedback circuit miR‐5188‐FOXO1‐PI3K/AKT‐c‐JUN in glioma." (PMID 32902145, 2020). "Besides, FOXO1 knockdown elevated protein levels of P‐PI3K, P‐AKT, CDK4, CCND1, c‐JUN, N‐cadherin and vimentin in glioma cells." (PMID 32902145, 2020). "Intriguingly, SP1 stimulated miR‐5188‐FOXO1‐PI3K/AKT‐c‐JUN axis, thus promoting glioma development." (PMID 32902145, 2020). "As a result, JUN inhibition could be considered a potential chemotherapeutic target for gliomas." (PMID 37375197, 2023). "Besides, AKT1, JUN, ALB, MAPK1, and TNF display good diagnostic value in glioma." (PMID 34873410, 2021). "The pro‐oncogene c‐JUN could regulate miRNA to augment glioma cell growth and metastasis." (PMID 32902145, 2020). "Our findings show that DET inhibits glioma invasion and proliferation by downregulating EGFR, JUN, and PI3K/AKT." (PMID 39850823, 2024). "Taken together, our data suggest that the natural product T4O exerts its anti-cancer effects by inducing JUN/GPX4-dependent ferroptosis and inhibiting cell proliferation, and T4O will hope-fully serve as a prospective compound for glioma treatment." (PMID 37375197, 2023). "We analyzed DNA methylation patterns at the JUN promoter and putative c-Jun regulated promoters (2 kb upstream/500 bp downstream relative to TSS) in GII/GIII-IDHwt and GIV glioma patients from the Glioma Atlas." (PMID 36850002, 2023). "By target harvesting, six core genes including AKT1, JUN, ALB, MAPK3, MAPK1, and TNF were screened from a total of 205 targets of luteolin against the glioma network." (PMID 34873410, 2021). "More importantly, AKT1, JUN, MAPKs, and TNF contribute to resistance to chemotherapy and radiotherapy, one of the greatest barriers in the treatment of glioma." (PMID 34873410, 2021). "While determining the mechanisms that miR‐5188 promotes glioma progression, we confirmed that overexpression of miR‐5188 up‐regulated protein levels of CDK4, CCND1, c‐JUN, N‐cadherin and vimentin." (PMID 32902145, 2020). "The feedback loop promoted glioma progression through activating the PI3K/AKT signalling, and this loop is augmented by the interaction between SP1 and c‐JUN." (PMID 32902145, 2020). "The results showed that expression levels of VEGFA, HK2, JUN, LDHA, and GAPDH were significantly high in glioma with wildtype-IDH and wildtype-1p/19q codeletion." (PMID 32500034, 2020). "miR‐5188 levels were negatively associated with FOXO1 mRNA levels (r = −0.3380, P = .0329), but positively correlated with c‐JUN mRNA levels (r = 0.2975, P = .0003) and SP1 mRNA levels (r = 0.2116, P = .0028) in the glioma specimens." (PMID 32902145, 2020). "miR‐5188, FOXO1, c‐JUN and SP1 expression were measured to illustrate their potential correlations in glioma and healthy brain tissues." (PMID 32902145, 2020). "Then, RT‐qPCR confirmed the decreased miR‐5188 expression in glioma cells under c‐JUN knockdown, suggesting c‐JUN as an upstream mediator of miR‐5188." (PMID 32902145, 2020).
glioma (continued). "In the current investigation, we identified the important role of miR‐5188 in glioma by examining miR‐5188 expression in glioma and non‐tumour brain specimens and the correlations between the expression of miR‐5188, SP1, c‐JUN and FOXO1." (PMID 32902145, 2020). "We used the Pan-Cancer and glioma TCGA datasets to investigate JUN expression in various types of cancers and corresponding normal tissues." (PMID 36850002, 2023). "This demonstrated a significant overexpression of MYBL2, FOXM1, ETS1, HIF-1A, and JUN in both glioma cohorts compared to non-neoplastic brain tissues." (PMID 35228525, 2022). "c‐JUN and SP1 mRNA levels were elevated in glioma in comparison with those in healthy brain tissues (P < .0001), whereas FOXO1 mRNA levels were down‐regulated in glioma (P = .0049)." (PMID 32902145, 2020). "Furthermore, the expression pattern of FOXO1, SP1 and c‐JUN in glioma samples and the correlations between FOXO1, c‐JUN, SP1 and miR‐5188 levels suggested an vital role of miR‐5188 in glioma development through FOXO1, c‐JUN and SP1 dysregulation." (PMID 32902145, 2020). "JUN expression can be applied to predict survival outcome, and high JUN expression indicates worse survival outcome in GBM (P = 001) and glioma (P = 0.026) based on the TCGA sequence database." (PMID 32984316, 2020). "In this work, c‐JUN‐augmented miR‐5188 transcription was facilitated by FOXO1‐PI3K‐AKT axis, suggesting the formation of miR‐5188‐FOXO1‐PI3K/AKT‐c‐JUN feedback circuit in glioma." (PMID 32902145, 2020). "Furthermore, we also found that levels of c‐JUN were decreased after SP1 knockdown through Western blotting in glioma cells, suggesting the regulation of SP1 on PI3K/AKT‐c‐JUN pathway." (PMID 32902145, 2020). "Besides, Western blotting revealed that miR‐5188 inhibition led to reduced protein levels of P‐PI3K, P‐AKT, CCND1, CDK4 and c‐JUN, but increased protein levels of FOXO1 in glioma cells with SP1 overexpression, suggesting that miR‐5188 was enhanced by SP1 through the PI3K/AKT pathway." (PMID 32902145, 2020). "Data from GEPIA2 also showed frequently increased FOS, JUNB, JUN, and ATF3 in glioma, especially GBM samples, compared to normal brain tissues." (PMID 39257581, 2024). "Hypoxia affected glioma cell lines differently from adenocarcinoma cell lines: 8 proteins were increased in gliomas (BAX, caspase 7, HIF-1α, c-JUN, MEK1, PARP 1 cleaved, Src, and VEGFR2) and none in adenocarcinomas." (PMID 22276931, 2012).
ovarian carcinoma (55 papers, 2000 to 2025). A malignant neoplasm originating from the surface ovarian epithelium. "In conclusion, we suggest that KRAS, NOXA, PUMA, c-FOS, and c-JUN may be associated with poor prognosis in ovarian cancer." (PMID 35807169, 2022). "Kaplan–Meier survival analysis spotlighted AKT1, JUN, EGFR, and VEGFA as potential diagnostic and prognostic biomarkers for ovarian cancer." (PMID 37964873, 2023). "In the context of ovarian cancer, JUN is often upregulated, driving the transcription of genes that promote tumor growth and invasion." (PMID 37964873, 2023). "Identified six cell types within ovarian cancer, including epithelial cells, fibroblast cells, T cells, B cells, macrophages, and endothelial cells, and the JUN pathway is a promising therapeutic target." (PMID 38022625, 2023). "Intriguingly, only the JUN signaling pathway was consistently found in all these three active modules, suggesting this TF as a potential driver for ovarian cancer." (PMID 34459128, 2021). "Together, our results suggest the JUN signaling pathway as a potential therapeutic target for ovarian cancer." (PMID 34459128, 2021). "Overall, these observations suggest that ILK regulates the JNK/c-JUN pathway in cisplatin-resistant ovarian cancer via modulation of DUSP8, MARVELD3, PDCD4, MAPK8IP1, MAPK8IP2, and HIPK3." (PMID 32260415, 2020). "We detected the expression of JNK and c-JUN protein in 10 ovarian cancer tissues and 10 benign ovarian tumors." (PMID 28666421, 2017). "Downregulation of GLI1 in cisplatin-treated ovarian cancer cells blocked the expression of c-JUN along with excision repair cross-complementing 1 (ERCC1), XRCC1 and xeroderma pigmentosum group D (XPD)." (PMID 26633513, 2015). "PD-L1 modulates angiogenesis by engaging in the c-JUN/VEGFR2 signaling axis in ovarian cancer." (PMID 41394850, 2025). "In summary, we provided evidence that KRAS, NOXA, PUMA, c-FOS, and c-JUN could be promising biomarkers in ovarian cancer." (PMID 35807169, 2022). "Moreover, dissection of the gene regulatory networks suggested the JUN signaling pathway as a potential therapeutic target for treatment of ovarian cancer, which was validated using the JUN/AP‐1 inhibitor T‐5224." (PMID 34459128, 2021). "In addition, we have previously shown that the JNK-1/c-JUN/miR-21 pathway contributes to cisplatin resistance in ovarian cancer cells." (PMID 32260415, 2020). "Furthermore, GLI1 downregulated ovarian cancer cells treated with cisplatin showed a switch in the phosphorylation pattern of c-JUN from Ser63/73 to Thr91/93." (PMID 26633513, 2015). "Moreover, single‐cell regulatory network inference and clustering (SCENIC) analysis reveals the gene regulatory networks and suggests the JUN signaling pathway as a potential therapeutic target for treatment of ovarian cancer, which is validated using the JUN/AP‐1 inhibitor T‐5224." (PMID 34459128, 2021). "Against this backdrop, our investigation delves into the intricate mechanisms governing CENP-O’s activity in ovarian cancer cells, shedding light on its downstream effects on gene expression, notably implicating EZH2 and JUN signaling pathways." (PMID 38890751, 2024). "Our previous study demonstrated that exogenous CCL2 promotes ovarian cancer cell proliferation by stimulating ERK signaling and regulating the JUN, RELB, and NF-κB2 expressions." (PMID 37445830, 2023). "The increase in enhancer histone marks around the JUN and FOS family gene loci in ovarian cancer cells was confirmed." (PMID 37779141, 2023). "In breast and ovarian cancer in particular, DYRK2 increases migratory activity of tumor cells through activation of c-JUN, c-Myc, and Snail signaling." (PMID 33804169, 2021).
ovarian carcinoma (continued). "We also determined that inhibition of DUSP6 promotes chemosensitivity of two different ovarian cancer cell lines, which coincided with increased expression of pro-apoptotic EGR1, and reduced expression of oncogenic c-JUN." (PMID 31164954, 2019). "Phosphorylation of c-JUN was increased rapidly with treatment in TRX-E-009-1 sensitive renal cell carcinoma (RCC) and NSCLC cell lines, confirming previously published results for TRX-E-002-1 in an ovarian cancer model." (PMID 29572477, 2018). "Analysis of a number human ovarian cancer cell lines showed that MAP2K4 expression is not detectable in 3 cell lines (SHOV3ip.1, SKOV-3 and HEY-A8) known to be metastatic in vivo while other members of the MAP2K4 pathway are intact including MEKK1, MKK7, JNK and c-JUN." (PMID 22355333, 2012).
COVID-19 (51 papers, 2020 to 2025). A disease caused by infection with severe acute respiratory syndrome coronavirus 2. "The results of Cox analysis revealed that the RACGAP1, TCF7L2, IRF7, DMD, and JUN were significantly associated with the development of COVID-19/BRCA (p < 0.05)." (PMID 36060002, 2022). "Cytokine storms caused by COVID-19 can be prevented by reducing JUN and FOS expression." (PMID 36380355, 2022). "Analysis of the transcription factors using the TRRUST database from our data (212 DEGs from GSE36854 and GSE21001) for MPXV infection and COVID-19 database by Metascape identified JUN, REL, STAT3, NFKB1, RELA, SP1, and so on." (PMID 37006463, 2023). "The proteins encoded by the ‘dark’ genes TRADD, FOS and DDGs RELB, JUN, IKBKG are involved in the MAPK signaling pathway, which is a potential signaling pathway for the spread and development of COVID-19." (PMID 37853311, 2023). "Here, we reported the mRNA upregulation of STAT3 together with its well-known downstream effectors c-FOS and c-JUN in COVID-19 patients compared with healthy controls." (PMID 35327634, 2022). "By constructing a protein-protein interaction (PPI) network, we ascertained FOS, NFKB1, NFKB1A, JUNB, and JUN as possible core target genes of quercetin for the treatment of COAD/COVID-19." (PMID 36249762, 2022). "Classical monocytes in the patient with acute stage of BNT162b2-myocarditis were similar to those in the patients with COVID-19 in terms of decreased level of JUN/FOS expression and increased regulon activity of CEBPB." (PMID 36225942, 2022). "Meanwhile, SARS-CoV-2 host genes, such as ACTB, KPNA2, and JUN, interact with SAMHD1, VCAM1, and HMOX1, in the PPI network, indicating possible mechanisms of COVID-19 associated stroke." (PMID 33732102, 2021). "There were three target genes (JUN, RELA, and AKT1) with a greater degree of significance, and they were identified as potentially relevant genes involved in the processes of HLJDD therapy of COVID-19-associated AKI." (PMID 37533739, 2023). "Therefore, JUN may exhibit differential expression after COVID-19 vaccination and may serve as a plausible signature gene." (PMID 36936955, 2023). "Interestingly, several enriched GO classifications in the COVID-19 group were associated with immune response, negative regulation of viral genome replication, activation of JUN, and regulation of NFKB pathways." (PMID 32646047, 2020). "Bronchoalveolar lavage fluid CD4+ T cells of patients with COVID-19 were TH1-skewed and showed de-repression of genes downregulated by Vitamin D which notably activates the recruiting of c-JUN and switches on the pro-inflammatory programs of TH1 cells." (PMID 37877121, 2023). "In our study, we found JUN modulates several pathways, such as the Toll-like receptor signalling pathway, TNF signalling pathway, Coronavirus disease—COVID-19, and NOD-like receptor signalling pathway." (PMID 37515084, 2023). "The key targets in the PPI network also present in the “Coronavirus disease - COVID-19” pathway included IL6, MAPK1, JUN, F2, and TNF." (PMID 38050310, 2023). "Heatmap showed upregulation of genes (e.g., TMPRSS2, JUN and CXCL8) related to the COVID-19 signalling pathway upon DCM treatment at a concentration of 200 μM, compared with concentrations of 0 μM and 100 μM." (PMID 37301869, 2023). "Among the enriched significant pathways, the Coronavirus disease-COVID-19-related pathways is the most significant pathway which involved most of the hHub-DEGs notably, CXCL8, EGFR, IL6, JUN, MAPK1, STAT3, TNF, and UBA52." (PMID 36016137, 2022). "Early studies have confirmed that JUN, FOS, and ATF3 are up-regulated in COVID-19 patients and correlated with the severity of COVID-19." (PMID 36380355, 2022). "The proteins overlapping with the enriched “B-cell Receptor Signaling Pathway (WP23),” JUN, HCLS1, PIK3AP1, and CRKL, were all increased in abundance in the COVID-19 spleen tissue, in addition to IL-18R1." (PMID 34710339, 2022).